IL15 (interleukin 15)
Diseases named in the same sentence as IL15 in open-access papers (continued):
Sharing a sentence is not in itself a finding about the gene and the disease.
tumor (continued). "Further arming CAR-NK cells with activating cytokines like IL-15 can enhance their in vivo persistence and improve their metabolic fitness, leading to enhanced tumor control." (PMID 38022679, 2023). "CD19 CAR T cells, IL-13Rα2 CAR T cells, and GD2 CAR T cells engineered to secrete IL-15 have shown increased expansion and in vivo anti-tumor activity in xenograft mouse models of Burkitt lymphoma, glioma, and metastatic neuroblastoma, respectively." (PMID 38090585, 2023). "The study concluded that IL-15-induced γδ T cells effectively suppressed tumor growth in vivo and prolonged the survival time of RCC-bearing patient−derived xenograft (PDX) mice." (PMID 38077392, 2023). "Tested in mouse models of lymphoma, engineered NK cells derived from cord blood, which were transduced with anti-CD19 CAR, IL-15, and inducible caspase 9, showed strong anti-tumor responses." (PMID 37514187, 2023). "In this study, we demonstrated the effects of IL-15 and IL-21 cytokines on the functions of NK-exos, highlighting their significant role in inducing potent anti-tumor effects in HCC cells." (PMID 37484408, 2023). "In contrast, DC vaccine coupled with IL-15 resulted in a negligible change in the tumor growth rate and animal survival compared to DC vaccine alone." (PMID 37598185, 2023). "In this study, we aimed to investigate the synergistic anti-tumor effects of NK-exos stimulated with IL-15 and IL-21 (NK-exosIL−15/21) in Hep3B cells." (PMID 37484408, 2023). "In conclusion, in this report we showed that KD033, the anti-human-PD-L1/IL-15 molecule currently in clinical study, had similar anti-tumor efficacies as its mouse surrogate, the anti-mouse-PD-L1/IL-15." (PMID 36454338, 2023). "We showed that in the Scid background, IL-15 deficiency promotes the development of T-ALL, revealing an unexpected tumor suppressor function for IL-15 in preventing the expansion of thymocytes that are otherwise destined to die in the thymus." (PMID 36765626, 2023). "In particular, IL-15, IL-12, and IL-18 secreted by DCs are strong inducers of NK cell proliferation, survival, and anti-tumor response, and are critically involved in the regulation of the anti-metastatic potential of NK cells." (PMID 37298470, 2023). "The flow cytometric assays were also performed in tumor resection model established to compare the efficacy of heterodimeric IL-15 and the MIST platform." (PMID 37875481, 2023). "In the context of HNSC, implementation of cytokine-based therapy with IL-2, IL-7, and IL-15 has demonstrated the ability to augment T cell activation, expansion, and anti-tumor effector function in patients." (PMID 37926766, 2023). "To date, a variety of myokines has been identified, including main driver mediators of an anti-tumoral tumor microenvironment such as the interleukins (IL) IL-7, IL-15, tumor necrosis factor (TNF) and interferon-gamma (INF-γ)." (PMID 37760634, 2023). "IL-15 has been shown to possess significant anti-tumor potential, making it an attractive target for cancer immunotherapy." (PMID 37251333, 2023). "In xenografts models of NB, NKT cells co-expressing anti-GD2 CAR and IL15 exhibited remarkable persistence, improved tumor infiltration, and enhanced anti-tumor activity." (PMID 37147740, 2023). "Interleukin-15 agonist molecules have shown that interleukin-15 agonists are effective in inhibiting tumor growth and preventing metastasis, and some are undergoing clinical trials." (PMID 37251333, 2023). "Even GC presenting in the tumor microenvironment together with IL-12, IL-15, and IL-18 induces the de novo expression of PD-1 on NK cells, which are associated with a strong immunosuppressive phenotype." (PMID 37114049, 2023). "In conclusion, pulsing zoledronate and co-stimulation by the combination of IL-2 and IL-15 lead to significant changes in in vitro anti-tumor activity and in the subclasses of stimulated γδ T cells." (PMID 37539052, 2023).
tumor (continued). "IL-15 is more effective in upregulating the expression of NKp46 and NKp30, which are involved in the recognition and killing of tumor- and virus-infected cells; IL-15 also increases the CD69 expression, which is an early activation marker on T and NK cells." (PMID 38106519, 2023). "Delivery of IL-15/IL-15Rα to tumor cells effectively mediated anti-tumor activity and sensitized the tumor microenvironment (TME) for therapy with αPD-L1 therapeutics, mainly by impacting NK cells." (PMID 38250068, 2023). "On the same line, Membrane Spanning 4-Domains A4A (MS4A4A)+ macrophages have been described for their anti-tumor function, in view of their ability to release pro-inflammatory cytokines, including IL-15 and IL-18, upon engagement of Dectin-1 by tumor cells." (PMID 37298470, 2023). "Accordingly, targeted delivery of IL-15 to tumor-specific T cells is of great essence for preventing systemic side effects and augmenting antitumor immunity of IL-15 therapy." (PMID 37875481, 2023). "When NK cells were depleted, the tumor control was impaired resulting in tumor spheroid growth unless IL-15/IL-15Rα was present in the culture." (PMID 37923822, 2023). "Enhanced activity of endogenous NK cells and CTLs in the tumor microenvironment mediated by RD-IL15 can be expected to complement direct cytotoxicity of IL-15-producing CAR-NK cells and enhance overall antitumor efficacy." (PMID 37686586, 2023). "Both monotherapies led to TRAMP-C1 tumor volume reduction (cyto-IL-15 by 63% and ADU by 84%) and increased survival (cyto-IL-15 to 41 and ADU to 45 days) compared with HBSS by day 28 post-treatment, which was the survival endpoint for the HBSS treated tumors." (PMID 37465665, 2023). "When adjusting for PS, tumor location, and stage, only IL-6 (HR = 1.25, 95% confidence interval (CI) 1.08–1.46) and IL-15 (HR = 2.23, 95% CI 1.48–3.35) remained significantly associated with OS." (PMID 36831406, 2023). "Cytokine-induced memory-like (CIML) NK cells, which differentiate after being activated with interleukin-12 (IL-12), IL-15, and IL-18, have been observed to possess enhanced anti-tumor responses." (PMID 36932395, 2023). "In xenograft models of aggressive B-cell lymphoma, the coinjection of this stabilized version of IL-15 together with CD19-specific CAR-T cells augmented CAR-T-cell performance eventuating in the longer survival of tumor-bearing mice." (PMID 36768665, 2023). "For instance, introducing optimized CAR constructs and membrane-bound IL-15 into iPS-T cells has led to comparable antitumor efficacy to primary CAR T cells in mouse tumor models." (PMID 37822720, 2023). "Co-expression of IL-12 and IL-15/IL-Rα using oHSV-1 has also been demonstrated to promote efficient tumor clearance in syngeneic colon and sarcoma models." (PMID 38022679, 2023). "These functional distinctions render IL-15 more favorable than IL-2 as a cancer immunotherapy given its ability to activate immune cells with tumor-suppressive ability and the potential for lower toxicity." (PMID 37371081, 2023). "In the case of BiKEs, one of the variable antibody domains recognizes CD16 and the other a targeted tumor antigen, whereas, TriKEs, in addition to these two domains, have an interleukin 15 (IL15) element that connects the two different antibody domains." (PMID 37228595, 2023). "IL-15, which is involved in the activation and maturation of anti-tumour T cells, including natural killer (NK) cells and CD8+ T cells, was demonstrated to be significantly increased following metformin treatment." (PMID 37601689, 2023). "The results showed that pro-IL-15 activated CD8+ T cells in the tumor reduced systemic toxicity and inhibited tumor growth." (PMID 37251333, 2023). "For example, IL-15 super-agonists can block TGFβ-mediated inhibition of NK cells leading to NK cell tumor cell killing." (PMID 37691935, 2023).
tumor (continued). "One of the myokines that affect the tumor microenvironment is interleukin (IL)-15, which is abundantly expressed in skeletal muscle and activates natural killer (NK) and T cell immunity." (PMID 38067295, 2023). "In one single patient study, CD5 CAR-T cells were modified to secrete IL-15/IL-15 sushi complex, as IL-15 has been shown to strengthen the anti-tumor response." (PMID 37108359, 2023). "In the following prophylactic tumor study, azido-labeled DC vaccine coupled with DBCO-IL-15 resulted in slower tumor growth and prolonged animal survival, in comparison with DC + IL-15 or DC alone." (PMID 37598185, 2023). "Membrane-bound IL-15/IL-15Rα (mbIL15) gene has been previously reported to improve the persistence and anti-tumour effect of genetically modified primary T cells in a xenograft animal model." (PMID 36509913, 2023). "In the neoplastic setting, IL-15 is likely produced by myeloid cells of the tumor microenvironment and cancer cells." (PMID 36831406, 2023). "In the review by Yang Y and Lundqvist A, reported the distinct roles of IL-2 and IL-15 in activating various functions in T and NK cells with a particular focus on the signals that participated in the resistance of tumor-derived immune suppressive factors." (PMID 37520880, 2023). "We showed that our next‐generation iNSCs provide a stable source of RANTES and IL‐15 cytokines locally at the tumor site, which enhanced CAR‐T‐cell migration and proliferation." (PMID 38023712, 2023). "Due to its complex functions, IL-15 has the potential as a tumor driver and an essential component of the anti-tumor immune response." (PMID 37153603, 2023). "BJ Bioscience, Inc. has developed the first tumor targeting IL-15 fusion protein, BJ-001, with a global patent." (PMID 36936961, 2023). "Interleukins, such as IL-2, IL-10, IL-12, IL15, and IL-21, and their receptors have been shown to be efficient mediators of anti-tumor immunity in preclinical cancer models." (PMID 37240247, 2023). "An animal model was used to study IL-15 expression level, tumor volume, cancer cell apoptosis, and NK cell infiltration after treadmill exercise." (PMID 37585912, 2023). "Significantly, the NIL-IM-Lip+L group had more CD8+ T cells, NK cells, and CTLs and fewer Treg cells in the tumour tissues than the IR780 + 1-MT + IL-15 + L group, showing better immune cell regulation in tumour tissues." (PMID 37076492, 2023). "Cytokines such as IL-15 or IL-2, which stimulate an anti-tumor immune response, have been shown to have a particularly high potential for use in immunotherapy against various tumors." (PMID 38002466, 2023). "IL-21-expressing cells exhibited greater cytotoxicity to tumor cells and greater survival in mice than IL-15 or IL-2 treated CAR-T cells despite higher levels of IFN-γ and Bcl-2 expression." (PMID 37064017, 2023). "Additional studies in other solid tumor models also demonstrate that IL-15 co-expression is a powerful method to enhance T-cell proliferation and anti-tumor activity in the solid TME." (PMID 38201551, 2023). "It has been shown that ex vivo-expanded NK cells exhibit higher cytokine secretion profiles and have stronger cytotoxicity against tumor cells, and the maintenance of this activation depends on the presence of IL-15 or IL-2." (PMID 38003255, 2023). "For example, anti-PD-1 antibody has been fused with IL-2, IL-15, or IL-21 to expand functional T cells and result in evident tumor remission." (PMID 38049832, 2023). "IL-15 secretion clearly improved cancer killing ability of MCAR15 Vδ2 T cell groups in repeated tumor challenges against OVCAR3-FG and OVCAR8-FG cells." (PMID 37938576, 2023). "The association was validated for IL-6 (HR = 1.25, 95% CI 1.08–1.46) and IL-15 (HR = 2.23, 95% CI 1.48–3.35) in an independent cohort adjusting for PS, tumor location, and stage." (PMID 36831406, 2023).
tumor (continued). "Mechanistically, we have illustrated its ability to induce IL-15 self-transpresentation in a multivalent manner and activate robust tumor-specific CTL responses." (PMID 37875481, 2023). "Bi-specific and tri-specific killer engagers (BiKE and TriKE molecules, respectively) also engage CD16 and tumor targets, with TriKEs the first to also incorporate an IL-15 moiety, delivering additional increased NK cell proliferation and survival signals." (PMID 37514187, 2023). "The results showed that in the tumor model, the level of IL-15 in plasma in pre-trained mice was significantly increased, which enhanced the identification and killing ability of NK cells." (PMID 37585912, 2023). "The flow cytometric assays were also performed in 4T1 tumor model established to compare the efficacy of heterodimeric IL-15 and the MIST platform." (PMID 37875481, 2023). "As a survival and anti-apoptotic factor for NK cells, IL-15 has a role in the survival and progression of NK cell neoplasms, stimulating tumor growth through the cytokine released by the tumor microenvironment (TME)." (PMID 37153603, 2023). "CD8+ T cells were then isolated from CT2A tumor-bearing mice and cocultured with APCs supplemented with 6.25ng/ml of recombinant IL15 for 3 days." (PMID 38268923, 2023). "Another study also observed robust colonization when S. Typhimurium was engineered for expressing interleukin 15 (IL-15) and two immune checkpoint inhibitors directly into the tumor microenvironment." (PMID 38116133, 2023). "We observed that immune cell-mediated tumor cell killing was facilitated when IL-15/IL-15Rα was produced by 624-MEL-GFP cells." (PMID 37923822, 2023). "The IL-15 component in TriKEs enhances NK cell mobility in vitro and a TriKE targeting the tumor stroma was able to enhance NK cell infiltration into the tumor in an animal model." (PMID 36911670, 2023). "BiNV-IL-15 obviously improved the percentage of tumor-infiltrating CD8+ T cells and downregulated the level of immunosuppressive Tregs in tumor, implying remarkable advantages over IL-15:IL-15Rα and IL-15:IL-15Rα+biNV." (PMID 37875481, 2023). "Knockout of the gene encoding for CIS (CISH) lowers the activation threshold of NK cells and enhances NK cell sensitivity to IL-15 improving their anti-tumor function." (PMID 38022679, 2023). "In another approach, GD2-targeting CAR-T cells with additional transgenic IL-15 expression showed an improved tumor control and survival of intravenously treated mice bearing patient-derived intracranial GBM." (PMID 37443804, 2023). "The addition of IL-15 (30 nM) or Avelumab (10 μg/ml) were each capable of reducing tumor growth (light blue and grey lines, respectively) with greater control when these therapies were combined (dark blue lines)." (PMID 36911670, 2023). "Anti-IL-6 treatment alone increased the expression of stimulatory cytokines (IL-7 and IL-15) in MDSCs compared to the tumor-bearing control." (PMID 37108179, 2023). "In mouse tumor models, pro-IL-15 significantly increased the proportion of stem-like CD8(+) T cells in tumor tissue and enhanced sensitivity to immune checkpoint inhibitors." (PMID 38049832, 2023). "In summary, pulsing zoledronate and additional administration of IL-15 modifies the anti-tumor activity and the differentiation of stimulated γδ T cells." (PMID 37539052, 2023). "Another IL-15-based immunocytokine, comprised of IL-15 and full-size anti-PD-L1 antibody (srKD033), showed a robust antitumor effect with even a single dose in several diverse syngeneic murine tumor models." (PMID 36839658, 2023). "IL-15 has the highest potential as a therapeutic tool when administered with the purpose of eliciting tumor eradication through the activation of NK cells and T-lymphocytes." (PMID 37153603, 2023).
tumor (continued). "Another engineering method is the incorporation of cytokine armoring genes, which leads to the production of cytokines required for T cell growth, including IL-15, IL-2, IL-7, IL-12, and IL-21, hence strengthening tumor-killing abilities." (PMID 37064017, 2023). "The biNV-IL-15 displayed the excellent capability of tumor recurrence inhibition in contrast to IL-15:IL-15Rα and IL-15:IL-15Rα+biNV, resulting in superior survival outcomes." (PMID 37875481, 2023). "Chou and his group demonstrated that deleting IL-15 from cancer cells eliminates the killer innate-like T cell protection and induces tumor growth." (PMID 37892995, 2023). "In breast, prostate, and colorectal cancer (CRC), (ILTCKs) have been identified, driven by tumor-derived IL-15." (PMID 37892995, 2023). "CD8+ T cell depletion changed the slope in the IL-15/IL-15Rα condition, resulting in reduced tumor cell killing." (PMID 37923822, 2023). "The retention of srKD003 in the tumor microenvironment facilitated IL-15-dependent cytotoxic cell expansion, activation of T and NK cells via PD-L1 inhibition, and IL-15 stimulation." (PMID 36839658, 2023). "Oportuzumab monatox, an Antibody–Drug Conjugate, and IL15 superagonist N-803 that enhance tumor targeting in combination with BCG, also showed encouraging first data." (PMID 36900247, 2023). "Compared with non-responders, patients with a partial response showed a significantly lower risk of relapse when their residual tumor exhibited high FOXP3, CD68, CD83, CD31 and CD34 content and IL15 expression but a low CD138 concentration." (PMID 37511057, 2023). "SRC is related to tumor suppressor factors, monocyte-macrophages and T cell chemokines by interacting with IL-15, colony stimulating factor 1 (CSF1), C-C motif chemokine ligand 5 (CCL-5), etc.." (PMID 36902024, 2023). "A recent pioneering trial reported aerobic exercise restricts PDAC tumour growth in mice, mediated by IL-15 signalling (a reputed ‘myokine’) and upregulation of anti-tumour immunity, ultimately sensitising tumours to therapy." (PMID 37735664, 2023). "There has been evidence in recent clinical trials that NK cells hyperproliferate and acquire an activated phenotype in patients receiving recombinant human IL-15, resulting in NK cell expansion in vivo and tumor shrinkage in two patients." (PMID 37081982, 2023). "Compared to DC vaccine alone or the combination of DC vaccine and IL-15, DC vaccine coupled with DBCO-IL-15 further inhibited tumor growth and prolonged animal survival." (PMID 37598185, 2023). "Among cytokines, βA most significantly increased the expression of Il1b, Il18 Il33, and Il15, both within tumor cells and fibroblasts." (PMID 38304252, 2023). "Administration of these IL-2 or IL-15 immunocytokines increased the safety and efficacy of the unconjugated cytokines and checkpoint antibody monotherapies or combinations in preclinical tumor models." (PMID 36454338, 2023). "The PD-1/PD-L1-inhibitor combined with the IL-15/IL-15Rα-nanovesicle complex significantly enhanced the anti-tumor responses." (PMID 37345176, 2023). "ILC1s are defined by the master transcription factor T-bet and are activated by the presence of IL-12, IL-15, and IL-18 to mount an anti-viral and anti-tumor response by producing effector cytokines IFNγ and TNF-α." (PMID 38567059, 2023). "IL-15 is an inflammatory cytokine that functions to promote cell growth and proliferation and is thought to have both anti-tumor and tumor-promoting activities, with its net effect likely being dependent on the particular tissue environment." (PMID 37175780, 2023). "This strategy has been shown to promote enhanced recruitment and prolonged tumor clearance when combined with engineered NK cell therapies, through OV expression of chemokines and activating cytokines such as IL-15." (PMID 38022679, 2023). "Cytokines such as IL-12, IL-15, and IL-18 enhance the anti-tumor capabilities of NK cells in vivo, leading to the suppression of liver tumorigenesis." (PMID 37539051, 2023).